FOXM1 (forkhead box M1)
Diseases named in the same sentence as FOXM1 in open-access papers (continued):
Sharing a sentence is not in itself a finding about the gene and the disease.
cancer (continued). "Finally, we will investigate the presence of FOXM1 in the tumor microenvironment via a relatively novel quantitative technology—single-cell RNA-Seq—by leveraging studies where cancer and non-cancer cells are identified and sequenced in the same samples." (PMID 39858603, 2025). "Indeed, several genes—such as BMYB, FOXM1, polo-like kinase 1 (PLK1), Aurora kinase A (AURKA), and CCNB1—regulated and suppressed by the DREAM complex are overexpressed in various cancers and are associated with a poor cancer prognosis." (PMID 39796178, 2025). "In addition, the expression of FOXM1 itself significantly positively correlates with aneuploidy in cancer." (PMID 39930267, 2025). "Moreover, newly discovered small molecules inhibitor of FOXO1 and FOXM1 have shown efficacy in preclinical cancer models, demonstrating the feasibility of targeting FOX transcription factors in vivo as well." (PMID 39777582, 2025). "Combining FOXM1 inhibitors with platinum based chemotherapeutic agents (cisplatin or carboplatin) might have a more drastic effect in aggressive SCLC cells as FOXM1 is known to confer chemoresistance in some other cancers." (PMID 40630538, 2025). "The expression level of FoxM1 significantly increased relative to that in para-carcinoma tissues." (PMID 40486884, 2025). "Previous studies have demonstrated the function of FOXM1 in various cancers." (PMID 38342795, 2024). "Interestingly, SPDEF binds to the promoter of FOXM1, which in a feedback loop is involved in cancer." (PMID 37644339, 2024). "FOXM1 pathway is the top enriched pathway in many human cancers." (PMID 38697979, 2024). "The findings of this study could provide a reference for further investigating the specific mechanism of FOXM1 in NSCLC or other cancers." (PMID 39020302, 2024). "Inhibition of FOXM1 is expected to sensitize cancer cells to conventional chemotherapy." (PMID 38425293, 2024). "Hence, we and others have focused on the development of small molecule inhibitors of FOXM1 and have been studying how these compounds, denoted NB compounds, are able to suppress the cancer-promoting activities of FOXM1." (PMID 38980505, 2024). "Given that EMT is a critical process for cancer cell migration and invasion, we investigated whether β‐sitosterol and FOXM1 play roles in EMT regulation in HCC." (PMID 38063438, 2024). "FOXM1 is one of the most intensively studied FOX transcription factor in cancer research." (PMID 38608123, 2024). "Targeting FOXM1 in AR-low TNBC may render cancer cells incapable of clustering their centrosomes and impair their ability to generate excess centrosomes." (PMID 39335162, 2024). "It has been reported that GAPDH may play an oncogenic role in cancer through DNA copy number amplification, altered promoter methylation, and/or FOXM1-regulated overexpression." (PMID 39188753, 2024). "As a transcription factor, FOXM1 controls the expression of numerous genes important for cellular proliferation, survival, and metastasis, making it a powerful and promising target in many human cancers." (PMID 39347707, 2024). "High expression or activation of ABL1 or FOXM1 overexpression are consistently observed in various cancers, but the possible links between them are largely unknown." (PMID 39060421, 2024). "In addition to the transcriptional regulation of target genes, the protein–protein interactions of FOXM1 play a critical role in cancer development and therapy." (PMID 39086352, 2024). "FOXM1 plays an essential role in the regulation of a wide spectrum of biological functions, including cell proliferation, cell cycle progression, cell differentiation, cell survival, and DNA damage repair in cancer cells." (PMID 38548749, 2024). "However, the overexpression of FOXM1 in cancer cells can lead to chemoresistance, as FOXM1 enhances DNA repair damaged by these drugs, thereby reducing their effectiveness." (PMID 39273409, 2024). "FOXM1 is a potent driver of tumor metastasis in multiple cancer types." (PMID 39335162, 2024).
cancer (continued). "The therapy-induced FOXM1 overexpression may explain the failure or reduced efficacy of these drugs in cancer patients." (PMID 38697979, 2024). "In addition, the decreased level of Cdc25C indicates that FOXM1 cooperates with other cell cycle regulators and oncogenes to induce proliferation in cancer cells." (PMID 39594778, 2024). "DNMT1/miR3a/FOXM1 axis plays an essential role in cancer stem-like traits in some liver cancer." (PMID 37922108, 2024). "Moreover, FOXM1 promotes the expansion of resistant cancer stem cells and increases the expression of ABC transporters responsible for drug efflux." (PMID 38398147, 2024). "FOXM1 regulation seems crucial in cancer progression and enhanced stemness in cancer." (PMID 37922108, 2024). "Pharmacological inhibition of FOXM1 could be a promising approach to sensitize therapy-resistant cancers." (PMID 38697979, 2024). "Thus, we discuss here the rationale for using FOXM1 inhibitors in combination with cytotoxic or other targeted therapies for the treatment of different cancers." (PMID 38398147, 2024). "FOXM1 is often dysregulated and more highly expressed in cancer stem cells." (PMID 38980505, 2024). "It is through the optimally coupled use of these two evolutionarily adaptive capacities—centrosome amplification and centrosome clustering—that cancer cells have the highest dividend and the transcription factor FOXM1 offers AR-low TNBC cells this critical capacity." (PMID 39335162, 2024). "Thus, FOXM1 overexpression confers resistance to chemotherapy to cancer cells by counteracting apoptosis." (PMID 39086352, 2024). "The human FOXM1 gene is located on the chromosomal band 12p13, which is frequently amplified in different cancers, including prostate cancer, breast adenocarcinoma, head and neck squamous cell carcinoma, nasopharyngeal carcinoma, and cervical squamous carcinoma." (PMID 38398147, 2024). "FOXM1, as a member of the Forkhead box transcription factor superfamily, is critically important to the proliferative ability of cells and the maintenance of self-renewal for cancer stem cells." (PMID 39022126, 2024). "To further determine whether FOXM1 is essential for cancer cell proliferation and the expression of cell cycle‐related genes, we knocked down FOXM1 in SW480 cells using siRNA." (PMID 38425293, 2024). "Importantly, in cancer cells, FOXM1 is often overexpressed, enhancing its ability to drive the expression of genes like KIF20A that are critical for cell proliferation and tumor progression." (PMID 39272816, 2024). "FOXM1 inhibitors can also be utilized as a maintenance monotherapy after chemotherapy to prevent relapse through their functions in suppressing stemness in cancer cells." (PMID 38398147, 2024). "These suggest that utilizing FOXM1 inhibition jointly with activation of ferroptosis might preferentially be directed to killing the cancer while sparing or having only limited effects on normal cells." (PMID 38980505, 2024). "Hence, we discuss the rationale and efficacy of all previously studied drug combinations with FOXM1 inhibitors for cancer therapies." (PMID 38398147, 2024). "FOXM1 is an important cell cycle regulator overexpressed in many cancers." (PMID 38425293, 2024). "Interestingly, STL001 increased the sensitivity of cancer cells to conventional cancer therapies by suppressing both the high-endogenous and drug-induced FOXM1." (PMID 38697979, 2024). "The most conventional cancer therapies studied here induce FOXM1 overexpression in solid cancers." (PMID 38697979, 2024). "Indeed FOXM1 has emerged as a key oncogenic driver of cell division, aggressiveness, metastasis, and drug resistance of cancer cells." (PMID 38697979, 2024). "FOXM1 additionally gives cancer cells with a high level of regulatory flexibility as it interacts with various regulatory proteins and pathways, allowing it to coordinate centrosome numbers and optimal clustering in diverse environments, ultimately leading to disease progression." (PMID 39335162, 2024).
cancer (continued). "Based on these results, we conclude that the gene expression regulated by STL001 is mostly the consequent of the inhibition of FOXM1 activity in cancer cells, thereby supporting the idea that the novel FOXM1 inhibitor STL001 is highly selective in its activity toward FOXM1." (PMID 38697979, 2024). "We next examined whether acquired resistance of the cancer cells to FOXM1 inhibitor could be reversed by a ferroptosis inducer such as DHA." (PMID 38980505, 2024). "Moreover, FOXM1-targeted therapies hold the potential to augment the effectiveness of conventional and targeted cancer treatments, including checkpoint inhibitors." (PMID 39594778, 2024). "Cancer hallmark signatures including E2F targets, MYC targets and PI3K-AKT-MTOR, molecular events including cell cycles and DNA replication, were also found highly enriched in FOXM1 + sgFOXA1 cells." (PMID 39687207, 2024). "However, this novel compound offers intriguing translational opportunities for the development of new anticancer agents as combination therapies targeting FOXM1 activities in a variety of human cancers." (PMID 38697979, 2024). "FOXM1 is one of the most commonly overexpressed genes in different human cancers." (PMID 37976368, 2024). "FOXM1 also affects radiotherapy outcomes in many cancer types, including CRC." (PMID 39607749, 2024). "FOXM1 can promote and maintain cancer cell stemness in various cancers by regulating the expressions of cancer stem cell phenotype driver genes and interacting with various signaling pathways, including Wnt signaling, the MAPK-ERK pathway, and the PI3K-mTOR pathway." (PMID 39086352, 2024). "Furthermore, we explored that FOXM1 high expression level predicted bleak prognosis in most types of cancer." (PMID 37159818, 2023). "We reasoned that aneuploid cancers might also require FOXM1 to compensate for deleterious CIN and hypothesized that cancers that allow propagation of CIN could be associated with a worse survival rate." (PMID 37452072, 2023). "FOXM1 has long been the target for developing anti-cancer agents." (PMID 38001498, 2023). "We discuss what is known about FOXM1 in MPNSTs relative to other cancers and how FOXM1 may be regulated by and/or regulate the most commonly altered players in MPNSTs, particularly in the MEK and CDK4/6 kinase pathways." (PMID 37686402, 2023). "Additionally, FOXM1 stimulates the expression of DNA damage repair-related genes in cancer cells, while inhibition of FOXM1 can enhance the sensitivity of cancers to chemical therapeutics." (PMID 37598210, 2023). "HnRNP C is significantly co-expressed with FOXM1 in cancers." (PMID 37759731, 2023). "M1-21 was selected and synthesized to bind FOXM1 in cancer cells." (PMID 37344857, 2023). "Due to the significant role played by FOXM1 in many human cancers, disruption of FOXM1 signaling could be an effective anti-cancer treatment strategy." (PMID 37174744, 2023). "FOXM1 has been reported to be activated in various cancers and its knockdown or inhibition showed therapeutic effects on various cancers, suggesting that FOXM1 might be an effector molecule that plays roles in neoplastic phenotypes in HS cells." (PMID 37231193, 2023). "Given FOXM1’s pivotal role as a quintessential transcription factor in myriad cancers, its interplay with oxidative stress potentially elucidates a mechanistic pathway through which FOXM1 might modulate tumor progression." (PMID 37817774, 2023). "Previous studies revealed that FOXM1 transcription could increase the expression of multiple genes important for cancers progression." (PMID 37601683, 2023). "Interestingly, circular RNAs (circRNAs), defined as crucial cancer regulators, decreased the expression of FOXM1 and promoted the expression of CENPA and CENPB to facilitate cell cycle progression." (PMID 36741311, 2023). "Therefore, phosphorylation of FoxM1 at Ser25 by PLK1 should be specified for cancer metastasis and direct activation of mesenchymal genes to acquire invasiveness." (PMID 37968723, 2023).
cancer (continued). "In addition to lung cancer, FOXM1 has been identified as supporting a CSC phenotype in many other cancer types, including breast, colorectal, hepatic, and pancreatic cancers." (PMID 37174744, 2023). "Furthermore, we explored the expression and effects of HMGA1 and FOXM1 in cancer, and their regulatory mechanism of cell cycle." (PMID 37240870, 2023). "Inhibition of FOXM1 leads to increased ROS induced DNA damage and apoptotic cell death in cancer." (PMID 37025658, 2023). "Both studies found a correlation between OTUB1 and FOXM1 protein levels in cancer samples." (PMID 38264570, 2023). "This allows FOXM1 to control the activity of anti-apoptotic genes like Bcl-2 and Survivin and to promote progression of the cell cycle, which supports cancer cell survival through replication defects and DNA damage that drive resistance to some chemotherapeutic drugs." (PMID 37370117, 2023). "Inhibition of FOXM1 perturb cancer cell proliferation and induce apoptosis." (PMID 37025658, 2023). "The ITPR1 variant could be altering the inflammatory and immune response involved in the pathogenesis of conditions such as cancer since this function is enriched in the MetaScape analysis by this and other candidate genes (FOXM1, CACNA2D1 and NTRK1)." (PMID 37175550, 2023). "In cancer, FOXM1 is a key regulator of several cancer-promoting phenotypes." (PMID 37174744, 2023). "Besides, a recombinant protein M1-138 has been generated to target FOXM1 in cancer cells by fusing the FOXM1 N-terminal domain (1-138aa) with a cell-penetrating peptide." (PMID 37598210, 2023). "Furthermore, cell-penetrating ARF26-44 peptide derived from tumor suppressor protein p19ARF and 9R-P201 peptide selected from a random dodecapeptide library against FOXM1 DBD can inhibit FOXM1 transcriptional activities in cancer cells." (PMID 37344857, 2023). "As INK4a/ARF loss is central to the oncogenesis of MPNST, these functional interactions with FOXM1 suggest that FOXM1 may also be an important driver in this cancer." (PMID 37686402, 2023). "As FOXM1 is known to regulate or be regulated by many of the frequently altered tumor suppressors and oncogenes in ANNUBPs and MPNSTs, it represents a novel and relevant factor warranting further study in this cancer." (PMID 37686402, 2023). "The critical role of FOXM1 in cancer confirms its importance for therapy and intervention." (PMID 37238726, 2023). "In this study, we intend to develop interfering peptides targeting FOXM1 for cancer treatment." (PMID 37598210, 2023). "The role of FOXM1 in various cancers has been a focal point in oncological research." (PMID 37817774, 2023). "Transcription factor FOXM1 is a potential target for anti-cancer drug development." (PMID 37344857, 2023). "The levels of FOXM1 are elevated in almost all clinical cancer types from the TCGA database." (PMID 37598210, 2023). "However, after the transfection of siRNA to knock down FOXM1, the pro-cancer effect of SNORD14E on EC cells was almost completely offset." (PMID 37667311, 2023). "We hypothesize that cancer cells in TNBC may enhance DNA replication activity by positively regulating FOXM1 expression and its downstream target genes, thereby promoting cancer cell occurrence and development." (PMID 37686305, 2023). "FOXM1 is one of the most important oncogenic TFs and it is overexpressed in many human cancers." (PMID 36424525, 2023). "The Forkhead box M1 factor (FOXM1) is a crucial activator for cancer cell proliferation." (PMID 38001498, 2023). "FOXM1 is known as a transcription factor promoting the progression of various malignant tumors." (PMID 37948132, 2023). "Indeed, in contrast to the fact that USP22 deletion resulted in a more than 50% reduction in lung metastases 4T1 cancer nodules, FoxM1 re-introduction restored USP22-null 4T1 cancer lung metastasis to a level of about 85–90% of the WT." (PMID 37398311, 2023). "M1-21 is a promising interfering peptide targeting FOXM1 for the development of anti-cancer drugs." (PMID 37344857, 2023).
cancer (continued). "Given that FOXM1 plays a crucial role in maintaining cancer stem cell properties, further studies should explore the effects of M1-20 on cancer stem cell populations during initial and recurring stages of cancer." (PMID 37598210, 2023). "Moreover, FOXM1 expression levels are significantly and positively correlated with hnRNP C expression levels in most TCGA cancer types (29 out of 32)." (PMID 37759731, 2023). "Thus, M1-138 provides a basis for further screening of so-called interfering peptides for the development of anti-cancer drugs targeting FOXM1." (PMID 37344857, 2023). "Moreover, knockdown of hnRNP C reduced the expression of FOXM1 protein, which is correlated with the positive co-expression of FOXM1 and hnRNP C in cancers." (PMID 37759731, 2023). "FOXM1 is a transcriptional master regulator of a number of cancers." (PMID 37667311, 2023). "In addition, the FOXM1 N-terminal domain can interact with other cancer-related transcription factors, such as β-catenin or Smad3, facilitating their nuclear import process to fully activate the classical WNT or TGF-β signaling pathway." (PMID 37598210, 2023). "Indeed, targeting of FOXM1 in combination with chemotherapy has shown benefit in enhanced anti-proliferative and pro-apoptotic effects in several pre-clinical cancer models." (PMID 37370117, 2023). "Research shows that FOXM1 can exert cancer-promoting functions." (PMID 37948132, 2023). "Because FOXM1 could be transcriptionally upregulated by itself, we further analyzed the correlation between RNF112 and FOXM1 in The Cancer Gene Atlas (TCGA) database." (PMID 37288663, 2023). "FOXM1 is upregulated during early cancer development, and contributes to tumorigenesis through stimulation of cell cycle progression via direct proliferation-driving targets like c-Myc, and suppression of senescence that can lead to cancer cell survival and relapse." (PMID 37370117, 2023). "Furthermore, the correlation between MRPL13 expression and FOXM1 expression was confirmed in various pan-cancers, which enriches the theoretical framework of MRPL13’s role in promoting the occurrence and progression of pan-cancer." (PMID 37827692, 2023). "Because we intended to analyze the anti-cancer effects of M1-21 in mice with wild-type backgrounds, we had to make sure that M1-21 could bind to mouse Foxm1." (PMID 37344857, 2023). "In addition, FOXM1 has experienced ubiquitination and deubiquitination mediated by ubiquitin E3 ligases and deubiquitinases in diseases and cancers." (PMID 36964598, 2023). "For example, FOXM1 overexpression, which also showed binding at both SRR124 and SRR134 in MCF-7 cells, has similarly been associated with poor patient outcomes in multiple types of cancer." (PMID 37738673, 2023). "Conversely, inhibition of FOXM1 reduced cell growth and contributed to chemosensitivity in cancer cells, indicating that targeting FOXM1 may be a promising strategy for cancers." (PMID 35313071, 2022). "Thus, FoxM1 is considered a prognostic factor and a promising candidate target for treating various cancers such as lung, breast, and prostate cancers." (PMID 35884976, 2022). "FOXM1 plays a major role in the progression of various cancers." (PMID 35887129, 2022). "However, despite this huge therapeutic potential, few studies have reported about FoxM1 inhibitor to modulate the activity and the transcriptional expression level of FoxM1 and related downstream genes during cancer development." (PMID 35884976, 2022). "Silencing of FOXM1 inhibits cancer cell proliferation and induces apoptosis." (PMID 35680842, 2022). "Therefore, there is potential for FOXM1 to be used as a biomarker for cancer prognosis and immunotherapy." (PMID 36435510, 2022). "In addition to regulating cell proliferation and migration, FOXM1 also affects angiogenesis, inflammation, chemotherapy drug resistance and radiation resistance in human cancers." (PMID 36435510, 2022).